IL21R (interleukin 21 receptor)
Description:
This is a receptor for interleukin-21.
Synonyms: CD360; NILR; IMD56
Tractability: Small molecule: a structure with a bound ligand is known. Antibody: its Gene Ontology location is reachable by antibodies, with high confidence; UniProt predicts a signal peptide or a membrane-spanning region; the Human Protein Atlas places it where antibodies can reach.
Gene: Protein-coding gene on chromosome 16 (27,402,174 to 27,452,050, forward strand). Ensembl gene ENSG00000103522.
Subcellular location: Membrane
Subcellular location (Human Protein Atlas): Cytosol; Plasma membrane
Pathways (Reactome):
Immune System: Interleukin-21 signaling
Gene Ontology:
Molecular function: cytokine receptor activity; protein binding; transmembrane signaling receptor activity; interleukin-21 receptor activity
Biological process: cell surface receptor signaling pathway via JAK-STAT; cytokine-mediated signaling pathway; immunoglobulin mediated immune response; natural killer cell activation; interleukin-21-mediated signaling pathway
Cellular component: plasma membrane; external side of plasma membrane; membrane
Genetic constraint (gnomAD): Loss-of-function variants: 16 observed, 38.49 expected, observed/expected ratio (o/e) 0.42, 90% interval 0.28 to 0.63. The upper end of that interval is the gene's LOEUF score, 0.63, which puts it in group 2 of 6, group 1 being the genes least tolerant of losing a copy. Missense variants: 572 observed, 671.95 expected, observed/expected ratio (o/e) 0.85, 90% interval 0.79 to 0.91. Synonymous variants: 281 observed, 287.35 expected, observed/expected ratio (o/e) 0.98, 90% interval 0.89 to 1.08.
Gene-disease validity (ClinGen):
ClinGen rates the evidence that IL21R causes each of these diseases.
immunodeficiency disease (autosomal recessive): Definitive. Disease in which there is a deficiency or defect in the mechanisms of immunity, either cellular or humoral.
Homologues: Orthologues: chimpanzee IL21R (99% identical), macaque IL21R (91% identical), dog IL21R (71% identical), guinea pig IL21R (70% identical), pig IL21R (69% identical), rat Il21r (62% identical), mouse Il21r (62% identical), tropical clawed frog il21r (30% identical). Paralogues in human: IL2RB (20% identical), IL4R (17% identical), IL9R (17% identical), CSF2RB (15% identical), EPOR (13% identical), MPL (12% identical), IL7R (12% identical).
Diseases named in the same sentence as IL21R in open-access papers:
IL21R is named in the same sentence as 145 diseases in open-access papers, as found by Europe PMC text mining. Sharing a sentence is not in itself a finding about the gene and the disease. The quoted sentences say what the papers report.
autoimmune disease (27 papers, 2008 to 2025). A disorder resulting from loss of function or tissue destruction of an organ or multiple organs, arising from humoral or cellular immune responses of the individual to their own tissue constituents. "Our study demonstrated that genetic variants in IL17RA and IL21R were associated with T1D susceptibility and that variants of IL-21R also predispose to other autoimmune diseases affecting thyroid and gastrointestinal tract tissues." (PMID 40979706, 2025). "The IL-21R rs3093301 (T/A) polymorphism has been described in different infectious diseases; however, few studies have associated it with autoimmune diseases." (PMID 37107636, 2023). "The increase in IL-21 levels in autoimmune diseases, and its association with RA clinical manifestations, such as the relationship with autoantibodies, suggests a regulation mechanism via IL-21/IL-21R." (PMID 37107636, 2023). "Previous investigations reported the association of diverse IL-21 and IL-21R polymorphisms with autoimmune disorders, such as systemic lupus erythematosus (SLE), multiple sclerosis, autoimmune thyroid diseases, and RA, in different populations." (PMID 37107636, 2023). "By attaching to its receptor, IL-21R, interleukin (IL)-21, a member of the IL-2 family, is implicated in biological processes in cancer and autoimmune disease." (PMID 37636564, 2023). "IL-21/IL21R polymorphisms have also been reported to be associated with risk for autoimmune diseases such as multiple sclerosis, autoimmune thyroid diseases, SLE, and RA." (PMID 37107636, 2023). "In recent years, the associations between the IL-21 gene or IL-21R gene polymorphisms and autoimmune diseases have been gradually reported." (PMID 23889847, 2013). "IL-21 has been implicated in autoimmunity disease via the IL-21R pathway." (PMID 23176102, 2012). "Since previous observations suggest that IL-21 and IL-21R may be associated with immunoglobulin production, autoantibody production, and B-lymphocyte hyperactivity, it is thought that IL-21 is involved in the pathogenesis of autoimmune disease." (PMID 22030011, 2011). "Alongside these findings, animal studies demonstrate that IL-21R deficient mice have normal T-cell and NK cell development but fail to develop spontaneous autoimmune disease suggesting that IL-21 plays a vital role in the development of autoimmune disease in rodents." (PMID 20553587, 2010). "This is consistent with the effects of IL-21R blockade on the outcome of pMHCII-NP therapy in various autoimmune disease models where we have documented TR1 cell-driven, IL-21-dependent Breg cell formation." (PMID 35672409, 2022). "Previous studies have demonstrated that IL21R is crucial for the differentiation of native T cells into Th17 cells and also plays a key role in the development of autoimmune disease." (PMID 35774982, 2022). "Modulating the IL-21/IL-21R signaling pathway is currently the focus of autoimmune disease treatment." (PMID 36293075, 2022). "As candidate agents, recombinant IL-21 and IL-21 receptor (IL-21R) antagonists have shown good efficacy and safety in clinical trials of carcinoma and autoimmune diseases." (PMID 28467480, 2017). "The abnormality of interleukin-21 (IL-21)-IL-21-receptor (IL-21R) system has been found in many autoimmune diseases including autoimmune thyroid diseases (AITDs)." (PMID 23889847, 2013). "Animal and clinical studies demonstrated the dysregulations of IL-21 and IL-21R in autoimmune diseases." (PMID 23889847, 2013). "Selective neutralization of the IL21/IL21R signaling pathway is a promising approach for the treatment of a variety of autoimmune diseases." (PMID 20504348, 2010). "A higher expression of IL-21R was also found in several autoimmune disorders, and blockade of the IL-21R pathway resulted in amelioration of the disease." (PMID 20057909, 2009).
autoimmune disease (continued). "Moreover, compared to rN and IM cells, aN and dnCS B cells in APs expressed a lower level of CXCR4, which is critical for GC reaction, and higher level IL‐21R, which promotes B cells to differentiate into PBs through the EF pathway in autoimmune disease." (PMID 36103567, 2022). "Conversely, IL-21/IL-21R blockade may also have therapeutic benefits in the treatment of autoimmune diseases and inflammatory conditions." (PMID 35777300, 2022). "Knowledge of the biological functions of IL-21 has led to clinical trials using this cytokine alone or in combination with other agents in treating metastatic cancers, and blocking antibodies to IL-21R are now being evaluated in clinical trials for the treatment of autoimmune diseases." (PMID 26966515, 2016). "However, the precise roles IL-21 and IL-21R in human autoimmune disease are still poorly understood." (PMID 22030011, 2011). "Thus, selective neutralization of the IL-21/IL-21R signaling pathway is a promising approach for the treatment of a variety of autoimmune diseases." (PMID 20420683, 2010). "Anti-IL-21R antibodies are potential therapeutics for the treatment of autoimmune diseases." (PMID 20420683, 2010). "In addition, clinical trials using blocking IL-21R mAb for autoimmune diseases are ongoing." (PMID 26966515, 2016). "Levels of IL-21 and IL-21R could be quite different in patients with autoimmune diseases." (PMID 23496892, 2013). "And the evident increase of serum IL-21 level in primary Sjogren’s syndrome (pSS) patients has positive correlation with the levels of gamma-globulin and erythrocyte sedimentation rate.These suggests that IL-21 and IL-21R may play a critical role in the pathogenesis of autoimmune diseases." (PMID 23889847, 2013). "In this sense, miR-20b and miR-30a suppress Th17 differentiation in experimental autoimmune diseases by targeting RORγt and STAT3 and IL-21R, respectively." (PMID 35370692, 2022). "Thus it is possible that CP-690550, through inhibition of IL-21R signaling, may also be efficacious in the CIA model by reducing IL-17 producing Th17 cells which have been proposed to play an important role in the pathogenesis of autoimmune diseases." (PMID 18234077, 2008).
lupus (20 papers, 2010 to 2025). "IL-21/IL-21R blockade is associated with decreased IL-6 and autoantibody production and has shown positive effects in preclinical trials in murine models of lupus and rheumatoid arthritis." (PMID 30984195, 2019). "Herber, D.; Brown, T.P.; Liang, S.; Young, D.A.; Collins, M.; Dunussi-Joannopoulos, K. IL-21 has a pathogenic role in a lupus-prone mouse model and its blockade with IL-21R.Fc reduces disease progression." (PMID 31557991, 2016). "Using a BXSB-Yaa SLE murine model, it was demonstrated that mice which are IL-21R-deficient show less lupus-like symptoms as compared to wild type BXSB-Yaa mice." (PMID 21959034, 2011). "Interestingly, BXSB-Yaa mice which are IL-21R deficient show less lupus-like symptoms as compared to their wild-type BXSB-Yaa mice." (PMID 31331400, 2019). "In an MRL-Fas(lpr) lupus murine model, blocking the IL-21 signal with an IL-21R.Fc fusion protein reduced the phenotypic disease severity, such as proteinuria, skin lesions, as well as renal injury and autoantibody production." (PMID 36293075, 2022). "Further examination of B cell differentiation in response to IL-21/IL-21R inhibition in a larger cohort of lupus patients with different clinical manifestations would be beneficial in the future." (PMID 36293075, 2022). "This could provide a mechanistic explanation for the association of polymorphisms in Il21 and Il21r and increased IL‐21 production with systemic lupus erythematosus (SLE)." (PMID 35801309, 2022). "In a murine model of lupus, the blockade of IL-21/IL-21R showed a reduction in B and T cell activation together with an interruption of disease progression." (PMID 33801294, 2021). "BXSB-Yaa lupus-prone mice showed higher circulating IL-21 and its mRNA transcripts compared with wild-type mice, and deletion of IL-21R would abrogate characteristic lupus phenotypes such as autoantibodies production and glomerulonephritis in these mice." (PMID 31835612, 2019). "In NZB/W mice, such IL-21R blocking even allowed reversing nephritis and halting disease progression in mice with preexisting lupus." (PMID 27635407, 2016). "In lupus MRL/lpr mice, activated CD4+ T cells secrete 10 times more IL-21 than control mice and IL-21R deficiency leads to reduced numbers of TFH cells." (PMID 27635407, 2016). "With the aim of defining TFH and B cell interactions, we analyzed the expression of IL-21R on lupus B cells." (PMID 24069401, 2013). "For example, in lupus, the IL-21 producing T cells have been shown to be increased, while the IL-21R expression on B cells appears to be decreased or unchanged." (PMID 23496892, 2013). "To better define TFH-B cell dialogue in lupus, we investigated the expression of IL-21R by B cells analyzed by three-color cytometry using anti-CD19, anti-CD27 and anti-IgD Abs." (PMID 24069401, 2013). "Inhibiting the IL-21/IL-21R pathway has been shown to be effective in ameliorating disease severity in lupus mouse models." (PMID 21959034, 2011). "Blocking the IL-21/IL-21R pathway by administration of a fusion protein has been fruitful in animal models of RA and in a lupus-prone MRL-Faslpr mouse model." (PMID 21959034, 2011). "Ab-01, a human antibody generated by phage display, recognizes the high affinity receptor for IL-21, IL21R, blocks IL21-mediated immune activation through antagonist engagement of IL21R and has shown efficacy in a mouse model of lupus." (PMID 20509950, 2010). "The blockade of IL-21/IL-21R is currently investigated in lupus (NCT03371251) and could be of interest in ITP." (PMID 33801294, 2021). "For example, compared with IL-21R-competent BXSB-Yaa mice for multiple parameters of SLE, the IL-21R-deficient Yaa mice showed none of the abnormalities characteristic of systemic lupus erythematosus (SLE)." (PMID 23889847, 2013). "However, we found a significant increase of memory B cells expressing IL-21R cells among CD19+ B cells in lupus patients compared to healthy individuals." (PMID 24069401, 2013).
lupus (continued). "Blockade of IL-21 with IL-21R-Fc fusion protein has resulted in fewer IgG glomerular deposits, circulating dsDNA auto-antibodies, total sera IgG1, IgG2a and lymphadenopathy in the lupus-prone MRL-Faslpr mouse." (PMID 23176102, 2012). "Corresponding to therapeutic efficacy, administration of IL-21R-Fc fusion protein to BXSB.B6-Yaa+/J mice, another model of lupus, decreased lymphocyte activation and circulating IgG1 levels." (PMID 23176102, 2012). "IL-21 is markedly elevated in autoimmune-prone mice and lupus severity is diminished in the absence of IL-21 or IL-21R signaling." (PMID 31057553, 2019). "For example, in vivo data show that blockade of IL-21 signaling using an IL-21 receptor Fc fusion protein (IL-21R Fc) decreases the disease severity in several murine models including collagen-induced arthritis, the MRL-Faslpr lupus model and the diabetic NOD model." (PMID 23496892, 2013). "For instance, overexpression of IL-21 induces inflammation; in the BXSB.6-Yaa+/J mouse model of systemic lupus erythematosus (SLE), affected mice exhibit elevated levels of IL-21, whereas IL-21R−/−BXSB.6-YAA+/J mice do not develop SLE." (PMID 40943537, 2025). "Similarly, IL-21R-deficient BXSB.B6-Yaa+/J mice presented none of the abnormal characteristics of systemic lupus erythematosus (SLE) in IL-21R-competent Yaa mice, including hypergammaglobulinemia, auto-antibody production and reduced frequencies of marginal zone B cells." (PMID 23176102, 2012).
rheumatoid arthritis (16 papers, 2008 to 2025). A chronic, systemic autoimmune disorder characterized by inflammation in the synovial membranes and articular surfaces. "The IL-21/IL-21R axis is a proinflammatory cytokine complex that has been associated with chronic inflammatory diseases including rheumatoid arthritis and inflammatory bowel disease." (PMID 24757284, 2014). "In an animal model of rheumatoid arthritis, blocking the IL-21 pathway by administration of a fusion protein (IL-21R.Fc) ameliorated disease severity." (PMID 21959034, 2011). "It enhances T cell activation, proliferation and secretion of pro-inflammatory cytokines such as TNFα and IL-21R has been shown to be over-expressed in inflamed synovial membrane and peripheral blood or synovial fluid leukocytes of rheumatoid arthritis patients." (PMID 18234077, 2008). "Furthermore, increased IL-21R levels have been reported in patients with rheumatoid arthritis, systemic sclerosis, and inflammatory bowel disease, including Crohn's disease and ulcerative colitis." (PMID 18773086, 2008). "First, therapies targeting IL-21/IL-21R are under development for type 1 diabetes, rheumatoid arthritis, and psoriasis, and our findings suggest that therapies blocking IL-21 or IL-21 signaling may be effective as a therapeutic target for inflammatory neuropathies." (PMID 39087473, 2024). "IL-21R is also highly expressed in synovial macrophages and fibroblasts of rheumatoid arthritis (RA) patients." (PMID 24757284, 2014). "IL-21R is overexpressed in the inflamed synovial membrane and in peripheral blood or synovial fluid leukocytes of rheumatoid arthritis (RA) patients." (PMID 23889847, 2013).
colitis (13 papers, 2011 to 2024). Inflammation of the colon. "Here we found that IL-21R.KO mice were more susceptible to DSS-induced colitis as compared with C57BL/6 mice." (PMID 27545302, 2016). "Furthermore, intervention of this feedback loop by IL-21 blockade, with IL-21R.Fc administration or IL-21 receptor deletion, attenuated Blimp-1 deficiency–mediated colitis and reinforced the circuit between Blimp-1 and IL-21 in the regulation of autoimmunity." (PMID 35503415, 2022). "We firstly examined the susceptibility of IL-21R deficient mice to DSS-induced colitis." (PMID 27545302, 2016). "Finally, we investigated the effect of IL-21R deficiency on Treg cell responses in LP of colon after DSS-induced colitis." (PMID 27545302, 2016). "IL21R may also aggravate colitis and promote colitis-associated colon cancer." (PMID 38723244, 2024). "In addition to the blockade of IL-21 by IL-21R.Fc neutralization, we further explored the effects of genetic disruption of IL-21 signaling on Blimp-1 deficiency–mediated colitis by crossing IL-21R–deficient mice with Blimp-1 CKO mice to generate a double-knockout (DKO) mouse model." (PMID 35503415, 2022). "The antibody-mediated abrogation of IL-21/IL-21R signaling led to the impaired expression of IFN-γ by mucosal CD4+ T cells from human subjects with colitis, suggesting an IL-21/IL-21R–triggered positive feedback loop of the TH1 immune response in the colon." (PMID 38498592, 2024). "Using a well-established and physiologically relevant murine model of Citrobacter rodentium–induced colitis, the mechanisms by which the IL-21/IL-21R signaling axis regulates colitis by enhancing the IL-12 responsiveness of CD4+ T cells were explored." (PMID 38498592, 2024). "Further studies are required to identify the exact contribution of IL-12Rβ1 and IL-12Rβ2 in mediating the proinflammatory functions of IL-21/IL-21R signaling during colitis." (PMID 38498592, 2024). "In this study, a previously less-defined function of the IL-21/IL-21R signaling in the regulation of colitis through interaction with the IL-12/IL-12Rβ2 signaling was identified." (PMID 38498592, 2024). "Specifically, it was found that the expression of Ifng, Il12rb1, and Il12rb2 was impaired in colonic CD4+ T cells of Il21r−/− mice during C. rodentium–induced colitis." (PMID 38498592, 2024). "We further treated CKO mice with IL-21R.Fc at the predisease stage (6 weeks old) and observed partial protection from colitis." (PMID 35503415, 2022). "It has been shown by other investigators that Il21r-/- mice express significantly higher levels of IFN-γ in the colon LP compared with WT counterparts during dextran sulfate sodium (DSS)-induced colitis." (PMID 30818341, 2019). "Our results demonstrate that IL-21/IL-21R signaling contributes to protection against DSS-induced acute colitis through suppression of Th1 and activation of Th2, Th17 and Treg responses in mice." (PMID 27545302, 2016). "In line with this, our data have shown that IL-21/IL-21R signaling protects mice from DSS-induced colitis through regulation of Th cell-mediated immune responses in intestinal mucosa." (PMID 27545302, 2016). "To elucidate the roles of IL-21/IL-21R signaling in DSS-induced colitis, we examined the effect of in vivo administration of rIL-21 on DSS-induced intestinal inflammation in C57BL/6 mice." (PMID 27545302, 2016). "A better understanding of the novel mechanisms by which IL-21/IL-21R signaling regulates bacterial-induced colitis will provide insights into the development of new therapeutic and preventive strategies to harness IL-21/IL-21R signaling or its downstream molecules to treat infectious colitis." (PMID 38498592, 2024). "Increased levels of IL-21 have been found in mice with chronic DSS-induced and TNBS-induced colitis, and IL-21 blockade by the addition of neutralizing IL-21R fusion proteins to DSS-treated mice mitigates colitis and inhibits the release of the main Th17 cytokines." (PMID 36769019, 2023).